TLR4 (toll like receptor 4)
Diseases named in the same sentence as TLR4 in open-access papers (continued):
Sharing a sentence is not in itself a finding about the gene and the disease.
malaria (continued). "While the involvement of TLR9, TLR4, and TLR2 in malaria immunity/pathology is evident from studies in both mouse malaria models and in humans, thus far none of the studies in endemic areas have revealed the association of TLR7 with human malaria immunity/pathology." (PMID 30619355, 2018). "First line of defense for pathogen recognition arisen with toll-like receptors TLR2, TLR4 and TLR5 in different infectious diseases such as malaria (adj pval 0.014), amoebiasis (adj pval 0.027) and legionellosis (adj pval 0.039) according to GEA over KEGG database." (PMID 29028836, 2017). "Both toll-like receptors two and four (TLR2, TLR4), part of the KEGG malaria pathway, had higher expression in the severe cases compared to the uncomplicated malaria group (2.07-fold higher for TLR2, 2.27- and 2.46-fold higher for the TLR4 probes)." (PMID 26961973, 2016). "Mean expression of TLR‐2 and TLR‐4 was significantly lower in children with acute CM and SMA compared with healthy controls, while HLA‐DR and CD86 expression was significantly lower in all three malaria groups." (PMID 27027867, 2016). "This study acknowledges that depletion of EPC is an important facet of malaria pathogenesis and identifies heme, CXCL10, TLR4 and circulating EPC levels as potential biomarkers for identification of individuals at risk of developing severe forms of the disease." (PMID 26555697, 2015). "Studies have confirmed that besides environmental factors and population diversity, polymorphisms in innate immunity genes such as Toll-like receptors (TLR2, TLR4, TLR9), chemokines, and cytokines as well as the heterogeneity in other immune-regulatory genes modulate malaria pathogenicity." (PMID 24066864, 2013). "Given that MBC stimulation can be driven by TLR4 and TLR9, the presence of circulating S. haematobium moieties may potentiate MBC response to malaria antigens by a TLR pathway, primed to an acute malaria infection." (PMID 22693628, 2012). "The overall data seem to indicate that none of the SNPs of TLR4, TIRAP and FCGR2A genes studied, assessed in Burundian children, play a role in modulating susceptibility to malaria and disease severity in this population." (PMID 22691414, 2012). "Despite the down-modulation of TLR2 and TLR4, stimulation with TLR agonists increased the levels of IL-8 produced by neutrophils from malaria patients before (medium versus LPS, p = 0.0010 or Pam, p = 0.0024) and after treatment (medium vs LPS, p = 0.0002; or Pam, p = 0.0017)." (PMID 22745844, 2012). "Notably, complement genes (C1QA, C1QB, C1QC), apoptotic genes (PDL1, PDL2, APOL1, APOL2, FAS), inflammatory caspases (CASP1, CASP5), TLR pathway genes (TLR1, TLR4, TLR5, TLR8), cytokines (IL6, IL10), and granzyme (GZMB) were among the genes upregulated during symptomatic malaria." (PMID 39161730, 2024). "The AS01B and AS02A adjuvants both contain TLR4 agonist MPL and the saponin QS-21, but AS01B is a liposome-based adjuvant whereas AS02A is an oil-in-water emulsion; RTS,S administered with either adjuvant appears to induce similar IgG subclass profiles in malaria-exposed children." (PMID 30798787, 2019). "Similar frequencies of TLR2, TLR4, TLR9, and MAL genetic polymorphisms in populations with different histories of malaria exposure suggest that these innate immune pathways have not been under strong selective pressure by malaria." (PMID 19317913, 2009). "Statistical analysis of non-malaria versus malaria subsets indicated there was a significant increase in the median fluorescence intensity of TLR4 (CD284) expression on EPC in malaria patients (non-malaria subjects, 33.7 vs malaria patients, 40.9, p = 0.04)." (PMID 26555697, 2015). "Adults with severe and mild malaria had increased expression of TLR2 and TLR4 on CD14+ monocytes and myeloid DCs and decreased expression of TLR9 on plasmacytoid DCs compared to adults with no history of malaria exposure." (PMID 19691558, 2009).
diabetic nephropathy (96 papers, 2014 to 2026). "Activation of the innate immune system and induction of pro-inflammatory cascade via TLRs, specifically TLR2 and TLR4, has been implicated in the pathogenesis of diabetic nephropathy." (PMID 40584714, 2025). "In diabetic kidney disease, tubular injury is associated with the upregulation of Toll-like receptor 4 (TLR4) and GSDMD." (PMID 39994107, 2025). "TLR4 signaling has been implicated in the pathogenesis of glomerular disease, including cryoglobulinemia in mice and diabetic nephropathy in humans." (PMID 32854642, 2020). "Preclinical evidence supported the concept that TLR2 and/or TLR4 are causative in diabetic kidney disease (DKD; Panchapakesan and Pollock, 2018)." (PMID 33442388, 2020). "Toll-like receptor-4 (TLR-4) has been implicated in the pathophysiology of diabetic nephropathy since its elevated expressions and increased stimulation in the diabetic milieu of the kidneys highly aggravate the tubulointerstitial inflammation." (PMID 31168342, 2019). "In the present study, we aimed to investigate the association between TLR4 polymorphisms and diabetic nephropathy." (PMID 24779014, 2014). "Secondly, although the tagging SNPs we selected covered all the common SNPs of TLR4, it is still possible that rare variants of TLR4 associated with diabetic nephropathy existed." (PMID 24779014, 2014). "In addition, SGP-1-1 stimulates the production of SOD and reduces the production of MDA by down-regulating the activation of TLR4/NF-κB p65 pathway to reduce oxidative stress caused by diabetic nephropathy." (PMID 38638866, 2024). "There is evidence that TLR-4 stimulation in MCs induces the production of a great variety of inflammatory molecules and the activation of complex molecular networks associated with diabetic nephropathy." (PMID 36233224, 2022). "Interestingly, TLR4 activation was highlighted as a potential mechanism in a genome-wide association study of diabetic kidney disease, linking keratan sulfate biology to inflammation." (PMID 32453760, 2020). "The pathogenic role of TLR4 in diabetic nephropathy has also been found." (PMID 32933213, 2020). "TLR4 is implicated in diabetic nephropathy, retinopathy, and cardiomyopathy." (PMID 31920992, 2019). "In this study, we aimed to investigate whether TLR4 variants are associated with diabetic nephropathy in the Chinese population." (PMID 24779014, 2014). "Therefore, in this study, we aim to investigate whether TLR4 genetic polymorphisms are associated with diabetic nephropathy and its related quantitative traits in the Chinese population." (PMID 24779014, 2014). "The first article by Ma J demonstrated that TLR4 played a key role in the pathogenesis of diabetic nephropathy, and TLR4 activation can lead to podocyte and tubular epithelial cell injury, inflammatory response, and interstitial fibrosis." (PMID 40584714, 2025). "“Toll-like receptor 4 promotes tubular inflammation in diabetic nephropathy” is the most cited publication with 48 citations." (PMID 40584714, 2025). "Most of them investigated the role of TLR4 in the pathogenesis of diabetic nephropathy and AKI, except for the article by Kawasaki T, which is associated with renal graft ischemia-reperfusion injury." (PMID 40584714, 2025). "Albumin-stimulated renal tubular epithelial cells induce macrophage M1-type polarization by releasing extracellular vesicles (EVs) containing miR-199a-5p, which targets the Klotho/TLR4 pathway and accelerates diabetic nephropathy progression." (PMID 39308872, 2024). "Burst analysis of references showed the most cited reference was entitled " Toll-Like Receptor 4 Promotes Tubular Inflammation in Diabetic Nephropathy"." (PMID 38758346, 2024). "High glucose increased the expression of Toll-like receptor 4 (TLR4) and inflammatory parameters in cells, suggesting a potential role of TLR4 in the progression of diabetic kidney disease." (PMID 39201774, 2024).
diabetic nephropathy (continued). "For example, miR‐26a‐5p alleviated acute lung injury by targeting TLR4 to suppress inflammation and apoptosis, and it decreased inflammation in diabetic nephropathy by targeting CHAC1/NF‐κB pathway." (PMID 36756710, 2023). "Recent studies have shown that SNHG16 exacerbates diabetic nephropathy by stabilizing TLR4 to regulate RAS and NF-κB pathway-mediated NLRP3 inflammatory vesicle activation." (PMID 37280692, 2023). "Recent studies have shown that SNHG16 exacerbates diabetic nephropathy through stabilizing TLR4/NF-κB pathway activation." (PMID 37280692, 2023). "MALAT1 enhanced diabetic nephropathy via suppression of miR-15b-5p and upregulation of TLR4 signaling." (PMID 36313695, 2022). "LncRNA MEG3 increased fibrosis and inflammation through regulating miR-181a, Egr-1 and TLR4 in diabetic nephropathy." (PMID 36313695, 2022). "Pae can improve the infiltration and activation of macrophages in diabetic nephropathy through inhibiting the Toll-like receptor 4 (TLR4) signaling pathway." (PMID 35184653, 2022). "The TLR is a sensor for bacterial components like lipopolysaccharide (LPS) and high levels of expression of TLR2 and TLR4 has been reported in blood cells of diabetic nephropathy patients." (PMID 33407253, 2021). "TLR4 signalling is important in tubulointerstitial inflammation and glomerular damage of diabetic kidney disease." (PMID 34502177, 2021). "For example, GSDMD expression was elevated in diabetic kidney disease, while suppressing the TLR4/NF-κB pathway induced GSDMD-related proptosis in DKD." (PMID 34692851, 2021). "Systemic tlr4 knockout (KO) has been shown to exert renoprotective effects in number of renal diseases, including diabetic nephropathy, lupus nephritis and nephrotoxic nephritis." (PMID 34568976, 2021). "MEG3 facilitated inflammatory response and fibrosis by regulating the miR-181a/Egr-1/TLR4 axis in diabetic nephropathy." (PMID 34672863, 2021). "DMDD alleviates diabetic nephropathy by mitigating kidney damage and inflammation via the inhibition of the TLR4/MyD88/NF-κB signaling pathway." (PMID 34975464, 2021). "Further, the progress of diabetic nephropathy was suppressed in TLR4 blockage Eritoran-administered diabetic mice." (PMID 33407253, 2021). "We and others recently revealed the pathogenic role of toll-like receptor 4 (TLR4) in the development and progression of diabetic nephropathy and crescentic glomerulonephritis." (PMID 32366231, 2020). "The TLR4/NF-κB signaling pathway plays multiple roles in coronary microembolization, gastroesophageal reflux disease, and diabetic nephropathy." (PMID 33292210, 2020). "During early stages of diabetic nephropathy, TLR4/NF-κB signaling is activated via upregulation of HMGB1, in turn promoting cytokine release, inflammation, and proteinuria." (PMID 31441362, 2019). "Molecular silencing of TLR4 in tubular cells with siRNA attenuated HG-induced IκB/NF-κB activation, indicating that the TLR4-NF-κB signal pathway plays an important role in diabetic nephropathy." (PMID 29861832, 2018). "Recently, it has been identified as a TLR4 endogenous ligand in diabetic conditions, HMGB1 and TLR4 level was increased in kidney tubular cells in diabetic nephropathy biopsies." (PMID 28542370, 2017). "The present study aims to examine the effect of TLR4 blocking to the progress of diabetic nephropathy promoted by P. gingivalis LPS." (PMID 29018490, 2017). "The present study aims to examine the effect of TLR4 blocking on the suppression of Pg-LPS-induced diabetic nephropathy." (PMID 29018490, 2017). "Sirolimus inhibited upregulated TLR4 and pro-inflammatory factor interleukin 17 in early-stage diabetic nephropathy in streptozotocin-induced diabetic rats." (PMID 27338360, 2016). "TLR4-mediated pathway also promotes dysfunction of mesangial cells that resulted in occluding of glomerular capillaries in Diabetic nephropathy." (PMID 26468333, 2015).
diabetic nephropathy (continued). "Abnormalities in glucose concentration have been reported to elevate and activate TLR4 to promote the secretion of inflammatory cytokines in mouse mesangial cells and contribute to diabetic nephropathy." (PMID 26468333, 2015). "Above all, it is convincible that TLR4 and its signal pathway play an important role in diabetic nephropathy." (PMID 24779014, 2014). "Given involvement of TLR4 pathways in these pivotal phases of diabetic nephropathy, strategies to inhibit TLR4 signalling should be explored." (PMID 24842252, 2014). "TLR4 has also been proved to accelerate the progression of diabetic nephropathy induced by hyperlipidemia." (PMID 24779014, 2014). "The study here investigates the effects of the periodontal pathogen Porphyromonas gingivalis lipopolysaccharide (LPS) which is a ligand for TLR2 and TLR4 in diabetic nephropathy." (PMID 24835775, 2014). "We have recently proposed that MRP8/TLR4 signaling plays an important role in hyperlipidemia-induced progression of diabetic nephropathy." (PMID 24558454, 2014). "Isoliquiritigenin could improve inflammation and oxidative stress through suppressing the Toll-like receptor 4 (TLR4)/NF-κB/NLRP3 signaling pathway in mice with diabetic kidney disease." (PMID 41357892, 2025). "Mudaliar H also revealed that TLR2 and TLR4 promote inflammation in diabetic nephropathy through activation of NF-κB, and their inhibition may be a new therapeutic target." (PMID 40584714, 2025). "Additionally, Cordyceps sinensis has the potential to mitigate renal damage and the associated inflammatory response by targeting the TGF-β1/Smad and TLR4/NF-κB signaling pathways in diabetic nephropathy animal models." (PMID 38645562, 2024). "In addition, the TLR4 signaling pathway is activated in the inflammatory response of various kidney diseases, such as acute ischemic kidney injury, diabetic nephropathy, and obesity-related nephropathy." (PMID 37856510, 2023). "It was reported that the lncRNA NEAT1/miR-34c/NLRP3 axis regulates pyroptosis activation and that the lncRNA MEG3/miR-181a/Egr-1/TLR4 signaling pathway promotes fibrosis and the inflammatory response, both of which mediate the progression of diabetic nephropathy." (PMID 34941711, 2021). "In addition, lncRNA NORAD upregulates TLR4 expression via targeting miR-520h to promote the progression of diabetic nephropathy." (PMID 34307380, 2021). "Moreover, upregulation of NORAD was demonstrated to affect the progression of diabetic nephropathy through targeting miR-520 h to increase the expression of TLR4." (PMID 33292272, 2020). "In vitro, researchers also observed increased TLR4 expression and proinflammatory cytokine synthesis when podocytes and adipocytes were exposed to both high glucose and NEFA (non-esterified “free” fatty acids), suggesting a key role of TLR4 in supporting inflammation in diabetic nephropathy." (PMID 32933213, 2020). "TLR4 blocker eritoran may be able to slow down the progress of Pg-LPS-induced diabetic nephropathy by suppressing the activation of circulating leukocytes in glomeruli and glomerular endothelial cells via TLR4 sensing intestinal bacterial LPS." (PMID 29018490, 2017). "The TLR blockages may prevent the progress of diabetic nephropathy since albuminuria and glomerular hypertrophy in the TLR4 KO-STZ mice is less pronounced than in the wild type-STZ mice." (PMID 29018490, 2017). "Our data indicate that TLR4 activation may promote inflammation, podocyte and tubular epithelial cell injury and interstitial fibrosis, suggesting TLR4 is a potential therapeutic target for diabetic nephropathy." (PMID 24842252, 2014). "Several studies have indicated that there may be a link between TLR4 pathway and diabetic nephropathy." (PMID 24779014, 2014).
diabetic nephropathy (continued). "MiRNA-146a and miRNA-223 are key epigenetic regulators of toll-like receptor 4 (TLR4)/tumor necrosis factor-receptor-associated factor 6 (TRAF6)/NOD-like receptor family pyrin domain-containing 3 (NLRP3) inflammasome pathway, which is involved in diabetic nephropathy (DN) pathogenesis." (PMID 39033184, 2024). "Moreover, administration of ATRA mitigated diabetic nephropathy in a TLR4-dependent manner." (PMID 36843131, 2023). "However, MEG3 may play a pro-fibrosis role because it has been demonstrated to enhance fibrosis and inflammatory responses in diabetic nephropathy through the miR-181a/Egr1/TLR4 axis." (PMID 35890132, 2022). "Furthermore, the levels of other inflammation-associated receptors (e.g., TLR2, TLR4, and RAGE) were elevated in diabetic nephropathy kidney tissue, together with DAMPs, such as AGEs, HMGB1, HSP70, and S100 calgranulins (e.g., S100A8 and S100A9), triggering their activation." (PMID 33478014, 2021). "Clinical approaches targeting TLRs in diabetic nephropathy include montelukast, which reduces renal inflammation by suppressing HMGB1/TLR4/NF-κB signaling." (PMID 40584714, 2025). "It was found that inhibition of SGLT2 in human diabetic nephropathy patients had a positive effect on inflammatory response (via inhibition of CD68, p65, TLR4, MCP-1, and osteopontin)." (PMID 40143180, 2025). "Drugs targeted to inflammatory cytokines, adrenocorticotropic hormone receptor (ACTH), TLR4/NF-κB, and TGF-β1 receptors partly prevent the occurrence and development of diabetic nephropathy in clinical trials." (PMID 38903987, 2024). "For instance, some scholars clarified that the Huangkui capsule mitigated renal tubular EMT in diabetic nephropathy in rats through the repression of the NLRP3 inflammasome and TLR4/NF-κB pathway." (PMID 36793762, 2023). "TLR4 mRNA expression was higher in patients with T2DM than in healthy individuals and shown to be involved in the development of tubular inflammation in diabetic nephropathy." (PMID 33478014, 2021). "Berberine ameliorated diabetic nephropathy by relieving inflammatory response and STZ-induced renal injury through inactivating the TLR4/NF-κB pathway." (PMID 34692851, 2021). "In this study, we found that tubular injury is accompanied by the up-regulation of Toll-like receptor 4 (TLR4) and GSDMD in patients with diabetic kidney disease." (PMID 31608008, 2019). "We have reported that toll-like receptor 4 (TLR4) and one of its endogenous ligands, myeloid-related protein 8 (MRP8 or S100A8), play an important role in the progression of diabetic nephropathy in mice." (PMID 24558454, 2014). "Moreover, TLR4 activation promotes podocyte injury and interstitial fibrosis in STZ-induced diabetic nephropathy in mice." (PMID 39769092, 2024). "ORI can also inhibit the inflammatory reaction of diabetes nephropathy rats, reduce the level of inflammatory cytokines, and alleviate the infiltration of inflammatory cells in renal tissue through inhibiting TLR4/p38-MAPK and TLR4/NF-κB pathways." (PMID 37032340, 2023). "TLR4 expression was increased in macrophages of diabetic nephropathy patients, while TLR2 expression was not changed." (PMID 37538798, 2023). "TLR4 and the complement system are widely involved in the occurrence and progression of various diseases, such as renal IRI, AKI and diabetic nephropathy, which can activate the transcription and expression of NFκB-mediated complement factor, thereby initiating the inflammatory cascade." (PMID 36973754, 2023). "TLR4 expression is also upregulated in the kidney in cisplatin-mediated AKI, cyclosporin nephrotoxicity, lupus nephritis, unilateral ureter obstruction, diabetic nephropathy and rhabdomyolysis-induced AKI." (PMID 33467524, 2021). "In addition, BBR is shown to block the activation of Toll-like receptor 4 (TLR4)/nuclear factor-kappa B (NF-κB) and the inflammatory response in an in vivo model of diabetic nephropathy." (PMID 32855766, 2020).